RNU6-519P (RNA, U6 small nuclear 519, pseudogene)
Gene: Small nuclear RNA gene on chromosome 8 (47,979,414 to 47,979,521, forward strand). Ensembl gene ENSG00000222522.
Homologues: Orthologues: chimpanzee U6 (99% identical), macaque U6 (86% identical), pig U6 (65% identical). Paralogues in human: RNU6-116P (82% identical), RNU6-1082P (81% identical), RNU6-1145P (81% identical), RNU6-46P (81% identical), RNU6-698P (81% identical), RNU6-1067P (80% identical), RNU6-1125P (80% identical), RNU6-1175P (80% identical), RNU6-1252P (80% identical), RNU6-200P (80% identical), RNU6-33P (80% identical), RNU6-345P (80% identical), and 1286 more.